ACSL4 (acyl-CoA synthetase long chain family member 4)
Diseases named in the same sentence as ACSL4 in open-access papers (continued):
Sharing a sentence is not in itself a finding about the gene and the disease.
tumor (continued). "ACSL4 inhibition reduces energy production and tumor growth without inducing apoptosis, suggesting a cytostatic effect that could be leveraged for combination therapies." (PMID 40507798, 2025). "Upregulation of ACSL4 inhibits the retinoic acid-inducible gene I-mitochondrial antiviral-signaling protein (RIG-I-MAVS) pathway, leading to decreased interferon-beta (IFN-β) production, impaired T-cell chemotaxis, and ultimately promoting tumor immune escape and progression." (PMID 41288931, 2025). "The sensitivity of many tumor cells to ferroptosis is limited by low or absent ACSL4 expression." (PMID 41288931, 2025). "Furthermore, ACSL4 catalyzes arachidonic acid to produce the lipid metabolism intermediate 5-hydroxyeicosatetraenoic acid (5-HETE), whose accumulation triggers cell membrane lipid peroxidation, leading to ferroptosis and suppressing tumor cell survival." (PMID 40510158, 2025). "Moreover, in tumor tissues, POL similarly inhibited the expression of ACSL4." (PMID 38503553, 2024). "By using specific inhibitors toward LPCAT3 ((R)-HTS-3) or ACSL4 (rosiglitazone) in enzymatic activity assays, we found that the substrate conversion rate of LPCAT3 did not exhibit differences between TRCs and bulk tumor cells, whereas ACSL4 catalytic activity was significantly decreased in TRCs." (PMID 38720107, 2024). "Increased expression of ACSL4 in the TNBC cell line MDA-MB-157 enhances the sensitivity of cancer tissue to the ferroptosis inducer RSL3, while deletion of ACSL4 prevents cancer cells from undergoing RSL3-induced ferroptosis and leads to increased tumor volume in vivo." (PMID 39664391, 2024). "While ACSL4 overexpression may confer some advantages, it may not fully compensate for these environmental constraints, leading to the observed lack of significant tumor size differences in the PBS-treated ACSL4 overexpression group compared to controls." (PMID 39563427, 2024). "Of ACSLs, ACSL5 was considered as the target gene, although lysoPCs may stimulate ACSL isoform activations and promote isoform‐specific biological processes, for example, ACSL1‐involved pro‐inflammation, ACSL3‐regulated androgen responsiveness or ACSL4‐and ACSL5‐related tumour suppression." (PMID 36639836, 2023). "This study demonstrated that ACSL4 correlated significantly with the recruitment of immune cells, including critical CD8+ T cells, in the BLCA microenvironment, which may have prevented tumor invasion and improved survival outcomes for BLCA patients." (PMID 34868963, 2021). "The expression of HER2 was negative in MCF-7 Tet-Off/ACSL4 tumor xenografts (data not shown)." (PMID 22808264, 2012). "Based on these results, we hypothesized that ACSL4, COX-2 and LOX-5 could be potential therapeutic targets for the control of tumor growth and that the use of a combination of inhibitors would result in potentiation of their effect compared to therapy with a single-drug." (PMID 22808264, 2012). "Notably, among the top-ranked CTD-suppressed genes, we found that five genes, including TOP2A, ACSL4, SQLE, CDK4, and SLC6A14 were significantly elevated in HCC clinical specimens, suggesting that NCTD targets to inhibit the expression of these genes to exert anti-tumor effects in HCC." (PMID 40271060, 2025). "However, one question remains: whether ferroptosis inducers like sorafenib can specifically target clinical tumor cells with high ACSL4 expression while sparing non-cancerous tissues with physiological ACSL4 expression." (PMID 40932861, 2025).
tumor (continued). "Furthermore, we hypothesized that CAR-T cell stimulation will sensitize tumor cells to ferroptosis via acyl-CoA synthetase long chain family member 4 (ACSL4) and phosphatidylcholine with diacyl-polyunsaturated fatty acid tails (PC-PUFA2) pathways, providing dual mechanisms of anti-tumor activity." (PMID 39849645, 2025). "Thus, preventing the biosynthesis of miR-22-3p or inhibiting the activation of its target gene, ACSL4, shows promise as a novel therapeutic strategy for neutralizing the impact of CVD on tumor progression by halting the exosome-mediated pathological communication between MI and tumor tissue." (PMID 39634266, 2024). "Mechanisms of ACSL4 involvement in tumor development may include iron-dependent, non-apoptotic, and cell death pathways, drug resistance caused by metabolic recombination, arachidonic acid-dependent tumorigenesis, steroid production and activation of intracellular pro-cancer signaling pathways." (PMID 35910359, 2022). "Targeting ACSL4 with the inhibitor PRGL493 reduced ATP production and suppressed tumor growth in vitro and in vivo, without inducing apoptosis, suggesting a cytostatic effect." (PMID 40507798, 2025). "We observed that overexpression of ACSL4 sensitized bulk tumor cells to RSL3 but did not confer an apparent effect in TRCs, despite the similar levels of ACSL4 expression between these two groups." (PMID 38720107, 2024). "Carbohydrate antigen 19 - 9 (CA19-9), which is the most widely used tumor marker in diagnosis of CHOL, is higher in the high ACSL4 expression group, though the P-value was not statistically significant." (PMID 37193981, 2023). "FBOX2, ACSL4 and PLIN2 showed strong expression in all six tumour samples but weak or no expression in non-tumour tissues." (PMID 28378759, 2017). "Therefore, as ACSL4 regulates ERα expression and the mTOR pathway, our results provide evidence that ACSL4 could be also an interesting target, in combination with 4-OHTAM, to restore tumor hormone dependence in tumors with poor prognosis and low survival rates." (PMID 26536660, 2015).
cancer (208 papers, 2010 to 2026). A tumor composed of atypical neoplastic, often pleomorphic cells that invade other tissues. "In RB1-deficient NEPC tumors, up-regulation of ACSL4 (a key enzyme promoting lipid peroxidation and triggering ferroptosis) renders cancer cells susceptible to ferroptosis inducers." (PMID 40746825, 2025). "ACSL4 has been implicated in neuroinflammation and systemic inflammatory responses, and its expression is associated with cancer prognosis through modulation of immune pathways." (PMID 41288931, 2025). "When ROS levels are elevated, inflammatory cytokines and ROS upregulate the expression of ferroptosis-inducing enzymes (e.g., ACSL4), induce iron overload and membrane lipid peroxidation, thereby rendering cancer cells more susceptible to ferroptosis." (PMID 41502519, 2025). "Tailored lipid and iron presentation can overcome ferroptosis resistance in ACSL4-deficient cancers." (PMID 39935430, 2025). "RB1 loss/E2F activation increases the sensitivity of cancer cells to ferroptosis by up-regulating ACSL4 expression and PUFAs enrichment." (PMID 39544949, 2024). "ACSL4 upregulated by bone morphogenetic protein 4 (BMP4) enhances the cancer cell fatty acid metabolism, which is associated with acquired drug resistance in EGFR-mutant NSCLC cells." (PMID 38539505, 2024). "Recently, resistance to induction of ferroptosis in a pancreatic cancer model has been attributed to the secretion of exosomes by cancer-associated fibroblasts that contain an miRNA (miR-3173-5p) that targets and down-regulates ACSL4." (PMID 37306503, 2023). "It was also reported that miR-3173-5p carried by exosomes derived from cancer-associated fibroblasts represses ACSL4 to inhibit ferroptosis in GEM-resistant pancreatic cancer." (PMID 37686142, 2023). "The same analysis was performed on the Kaplan-Meier mapping database and ACSL4 expression was associated with prognosis for 14 cancer types." (PMID 35126480, 2022). "A major finding in this study was that ACSL4 expression was associated with levels of immune invasion across multiple cancer types." (PMID 35126480, 2022). "Low ACSL4 expression was associated with poor prognosis in six other cancers, including BLCA, CESC, HNSC, PAAD, STAD and TGCT." (PMID 35126480, 2022). "The literature reports that loss ACSL4 will promote cancer progress and enhanced ACSL4 expression will result in better clinical outcomes in tumors." (PMID 36467072, 2022). "Emerging evidences showed that dysregulated expression of ACSL4 was tightly associated with various diseases and especially with cancers." (PMID 35910359, 2022). "The mechanism underlying this context-dependent role of ACSL4 in different cancer types is still elusive." (PMID 34053456, 2021). "ACSL4 regulates signal transduction pathways implicated in cancer, such as the mTOR pathway, and its overexpression has been shown to decrease ERα levels." (PMID 31311992, 2019). "The expression of ACSL4 has been linked to the sensitivity of cancer cells to ferroptosis." (PMID 39804099, 2025). "Finally, we identify a subtype of cancer-associated fibroblasts (CAFs), ACSL4+CAFs, which impact patients’ overall survival (OS) and sensitivity to immunotherapy." (PMID 39238647, 2024). "In this issue of the JCI, Wang and colleagues examined how RB1 loss may sensitize cancer cells to ferroptosis inducers through elevation of ACSL4, a key enzyme that promotes lipid peroxidation and triggers ferroptosis." (PMID 37183818, 2023). "Indeed, the activation of ferroptosis in cancer cells requires the overexpression of ACSL4, of which the functional product enters into the PUFAs metabolism and is related to the depletion of glutathione reserve, a hallmark of cancer cells proliferation." (PMID 36829917, 2023). "In addition, we analyzed the effect of ACSL4 mutation on immune cell levels in various cancers by Mutation module." (PMID 35126480, 2022).
cancer (continued). "In addition, this study further analyzed the association between ACSL4 and immune cell biomarkers in different cancers." (PMID 35126480, 2022). "The induction of ferroptosis is also resistant to chemoradiotherapy in cancer, and the transcriptional coactivator, Yes-associated protein, is activated in drug-resistant cancer cells, thereby enhancing ferroptosis sensitivity by activating two iron-promoting factors, ACSL4 and TFRC." (PMID 36686700, 2022). "ACSL4 behaves as a crucial regulator in lipid metabolism, ferroptosis, and immune response, which contributes to its tight association with the onset and progression of various cancers." (PMID 35910359, 2022). "Although changes in the ACSL4 gene in our data affect immune cell infiltration levels in only a few cancer types, it also suggests that ACSL4 mutations or copy number abnormalities are closely associated with immune cell infiltration and affect prognosis in UCEC, SARC, BRCA and OV." (PMID 35126480, 2022). "We found that ACSL4 was associated with prognosis of four cancer types." (PMID 35126480, 2022). "In this context, ACSL4 may be capable of identifying abnormalities to serve as risk, diagnostic or prognostic markers as well as therapeutic targets in a wide range of cancers." (PMID 35910359, 2022). "Importantly, there is emerging evidence that dysregulated expression of both ACSL3 and ACSL4 is associated with disease and especially with cancer." (PMID 32286604, 2020). "It has been demonstrated that Acyl-CoA synthetase 4 (ACSL4) enzyme expression is elevated in cancer cells, which promotes an aggressive phenotype associated with the dysregulated production of eicosanoids, particularly in breast, colon, hepatocellular and prostate cancer." (PMID 31311992, 2019). "In addition to their key gatekeeper roles in fatty acid metabolism in normal tissues, ACSL3 and ACSL4 expression levels are frequently altered in cancer, and this is sometimes associated with a more aggressive metastatic phenotype and a poor prognosis." (PMID 29450800, 2018). "We verified expression of ACSL4 in genetically unmodified parental HT-29 and L929 cells by Western blotting, thus ruling out the possibility that loss of ACSL4 expression might be a protective mechanism of cancer cells to avoid their own demise by ferroptosis." (PMID 28551825, 2017). "This may be associated with the different roles of ACSL4 in distinct cancers." (PMID 35910359, 2022). "Therefore, in order to understand more completely how fatty acid metabolism is compartmentalised in cancer cells, it is first necessary to determine the organelle-association patterns for endogenously ACSL3 and ACSL4 in different cancer subtypes and cell lines." (PMID 29450800, 2018). "Since PUFAs cannot be synthesized de novo, mesenchymal cancers regulate the ratio of PLs with PUFAs and MUFAs by upregulating ACSL4, fatty acid desaturase 2 (FADS2), and ELOVL fatty acid elongase 5 (ELOVL5)." (PMID 41596341, 2026). "In terms of lipid metabolism, cancer stem cells (CSCs) reduce the sensitivity to lipid peroxidation by downregulating ACSL4 expression, thereby decreasing the abundance of PUFA-PLs in the cell membrane." (PMID 40932861, 2025). "Deleting ACSL4 significantly eliminates ionizing radiation-induced ferroptosis and promotes radioresistance, thus highlighting the crucial role of ACSL4 in cancer treatment." (PMID 39975561, 2025). "Extensive studies have shown that ACSL4 is upregulated in many types of human cancers and is involved in many biological functions, including cancer cell proliferation." (PMID 38564125, 2025). "Dysregulated expression of ACSL4 has been reported in various types of cancers, including colorectal cancer, ovarian cancer, and breast cancer." (PMID 38564125, 2025). "Studies have reported that short interfering RNA‐mediated deletion or chemical inhibition of ACSL4 in cancer and intestinal epithelial cell lines protects cells from radiation‐induced ferroptosis in vitro." (PMID 39425547, 2025).
cancer (continued). "This is particularly important as others have recently shown that elevated ACSL4 modulates cancer cell membrane lipid composition in vivo and makes them susceptible to T cell-derived IFNγ induced ferroptosis." (PMID 40382332, 2025). "Recent studies have identified crucial roles of ACSL1, ACSL3, and ACSL4 in ferroptosis, thereby opening new avenues for exploring their involvement in tumorigenesis and cancer therapy." (PMID 41288931, 2025). "ACSL4 enhances cancer cell sensitivity to ferroptosis by altering cellular lipid composition, thereby promoting the accumulation of lipid peroxides (LPO)." (PMID 41288931, 2025). "Beyond HCC, ACSL4 is highly expressed in hepatoblastoma and is considered a key gene in the proliferative subtype of this cancer." (PMID 41288931, 2025). "In summary, medium-chain fatty acids are capable of selectively sensitizing cancer cells to the ferroptosis that is mechanically associated with the induction of fatty acid transporter CD36 and lipid peroxidation related enzyme ACSL4." (PMID 40077664, 2025). "Particularly, ACSL4 exhibited the most predominant negative correlation with PEBP1/STK11 co-expression across multiple cancer types, suggesting an inhibitory role in fatty acid metabolism." (PMID 40806276, 2025). "ACSL4-mediated ferroptosis is a molecular event that exerts a crucial regulatory function in cancer development." (PMID 40158112, 2025). "ACSL4 plays a promoter or suppressor role in tumors depending on the specific cancer type and tissue environment." (PMID 40050614, 2025). "Recent studies have highlighted ACSL4’s significant involvement in various cancers and neurodegenerative diseases." (PMID 40612574, 2025). "The up-regulation of ACSL4 expression and enhancement of lipid peroxidation rate induced by RB1 loss further intensify cancer cell dependence on GPX4 for iron homeostasis blockade." (PMID 40746825, 2025). "FASN, ACACA, ACLY, and ACSL4 are considered key enzymes in lipid metabolism, and previous studies have shown that they can promote the proliferation of various cancers." (PMID 39891099, 2025). "Inhibition of ACSL4 can overcome radioresistance by suppressing the DNA damage response, thereby promoting apoptosis in cancer cells during radiotherapy." (PMID 41288931, 2025). "Simultaneously, utilizing advanced analytical techniques from bioinformatics and transcriptomics, we will further explore the expression of ACSL4 in various types of cancer and its clinical correlation with patient prognosis." (PMID 40932861, 2025). "In contrast, the activation of the ACSL4 and Nrf2-Keap1 pathways can induce ferroptosis in cancer cells, contributing to cancer suppression." (PMID 40822852, 2025). "Herein, the expression of ACSL4 was briefly evaluated in OS samples and para-carcinoma tissues by immunohistochemical (IHC) staining." (PMID 38564125, 2025). "ACSL4 mRNA expression can be upregulated in certain cancer cells and thereby contribute to increased ferroptosis sensitivity." (PMID 38908072, 2024). "In cancer therapy, directing interventions at ACSL4 has exhibited efficacy in triggering ferroptosis and impeding cell viability, presenting itself as a promising therapeutic approach." (PMID 38562143, 2024). "Studies have shown that ACSL4 expression is aberrant in clinical cancers, and some of these expression aberrations correlate with poor patient survival." (PMID 39311951, 2024). "The roles of ACSL4 regulated by lipid‐metabolic related lncRNAs and circRNAs of cancer mainly involve into two biological progresses." (PMID 37939296, 2024). "Cell-cell communication analysis reveals SDC1 as an important target on cancer cells interacting with ACSL4+CAFs." (PMID 39238647, 2024). "We performed cell-cell communication analysis between cancer cells and a few specific ferroptosis-related TME cell subpopulations, and the results yielded that SDC1 was a crucial target associated with ACSL4+CAFs." (PMID 39238647, 2024).